AMIGO3 (adhesion molecule with Ig like domain 3)
Description:
May mediate heterophilic cell-cell interaction. May contribute to signal transduction through its intracellular domain (By similarity).
Synonyms: ALI3; AMIGO-3
Tractability: Antibody: UniProt predicts a signal peptide or a membrane-spanning region.
Gene: Protein-coding gene on chromosome 3 (49,716,829 to 49,719,684, reverse strand). Ensembl gene ENSG00000176020.
Subcellular location: Membrane
Subcellular location (Human Protein Atlas): Actin filaments
Gene Ontology:
Molecular function: protein-containing complex binding
Biological process: brain development; heterophilic cell-cell adhesion; positive regulation of synapse assembly; negative regulation of neuron projection development; nervous system development
Cellular component: membrane
Genetic constraint (gnomAD): Loss-of-function variants: 9 observed, 7.53 expected, observed/expected ratio (o/e) 1.19, 90% interval 0.71 to 1.84. That is too few expected variants to judge how well the gene tolerates losing a copy. Missense variants: 771 observed, 746.75 expected, observed/expected ratio (o/e) 1.03, 90% interval 0.97 to 1.1. Synonymous variants: 315 observed, 345.87 expected, observed/expected ratio (o/e) 0.91, 90% interval 0.83 to 1.
Homologues: Orthologues: chimpanzee AMIGO3 (99% identical), macaque AMIGO3 (96% identical), rabbit AMIGO3 (84% identical), dog AMIGO3 (84% identical), pig AMIGO3 (83% identical), guinea pig AMIGO3 (81% identical), rat Amigo3 (79% identical), mouse Amigo3 (76% identical), tropical clawed frog amigo3 (43% identical), zebrafish amigo3 (40% identical). Paralogues in human: AMIGO1 (35% identical), AMIGO2 (33% identical).
Diseases named in the same sentence as AMIGO3 in open-access papers:
AMIGO3 is named in the same sentence as 5 diseases in open-access papers, as found by Europe PMC text mining. Sharing a sentence is not in itself a finding about the gene and the disease. The quoted sentences say what the papers report.
demyelinating disease (1 paper, 2021). A broad group of disorders that affect the myelin sheaths that cover the neurons. "Thus, compared to Lingo-1, our study highlights the potential of AMIGO3 as a more effective therapeutic target to decrease abnormal neural circuit formation in the immature brain after SC and demyelinating diseases, although further studies are required to fully elucidate the underlying mechanism." (PMID 34650403, 2021).
fibromyalgia (1 paper, 2023). A chronic disorder of unknown etiology characterized by pain, stiffness, and tenderness in the muscles of neck, shoulders, back, hips, arms, and legs. "Several genes/loci have been reported more than once in CWP, fibromyalgia, and MCP, including EXD3, SLC39A8, AMIGO3/GMPPB/RNF123, C6orf106, FAF1, SLC24A3, and LINC01065/LINC00558." (PMID 37144689, 2023).
injury (1 paper, 2021). Damage inflicted on the body as the direct or indirect result of an external force, with or without disruption of structural continuity. "Due to the similar protective effect of Lingo-1 and AMIGO3, a combinational treatment of inhibiting both may exert synergistic effect to alleviate convulsion-induced brain injury." (PMID 34650403, 2021).
tumor (1 paper, 2026). "In contrast, AMIGO1 and AMIGO3 have not been consistently associated with tumor aggressiveness or adverse prognosis in these settings and do not exhibit robust expression changes in PAAD." (PMID 41583520, 2026).
AMIGO3 also shares sentences with these, for which no sentence is quoted: cancer (1 paper).